IL6 (interleukin 6)
Diseases named in the same sentence as IL6 in open-access papers (continued):
Sharing a sentence is not in itself a finding about the gene and the disease.
rheumatoid arthritis (continued). "IL-6 is considered to be the driving signal of many inflammatory and lymphoproliferative diseases, such as rheumatoid arthritis and Castleman's disease, and several therapies have been developed to target IL-6 signaling pathway." (PMID 34054555, 2021). "This miRNA has been previously shown to also be significantly downregulated in the sera of rheumatoid arthritis patients, where patients also exhibit upregulated IL-6." (PMID 34564316, 2021). "Emerging evidence indicates that a humanized anti-IL-6 receptor antibody, tocilizumab, can effectively block IL-6 signaling and has beneficial effects in rheumatoid arthritis, juvenile systemic idiopathic arthritis, and Castleman’s disease." (PMID 34253862, 2021). "Equol administration in a rheumatoid arthritis mouse model improved arthritis-induced bone mineral density and suppressed the expression of IL-6 and its receptor in inflamed areas." (PMID 34835997, 2021). "TNFα and IL6 are up-regulated in many inflammatory diseases, such as rheumatoid arthritis, inflammatory lung diseases and tumors." (PMID 34262459, 2021). "IL-1β mainly participates in the immune response and tissue repair in response to inflammatory diseases, especially rheumatoid arthritis, and IL-6 has a similar function." (PMID 33732152, 2021). "Vitamin B-6 has also been associated with inflammation (CRP) in the NHANES study (2003-2004), and B-6 supplementation in rheumatoid arthritis patients has been shown to reduce levels of IL-6 and TNF-α." (PMID 34836049, 2021). "Curcumin has been found to significantly reduce H3ac levels in the IL-6 promoter as well as IL-6 mRNA expression in rheumatoid arthritis synovial fibroblasts (RASFs)." (PMID 33915757, 2021). "Correspondingly, inhibition of IL-6 trans-signalling is sufficient to block inflammatory bowel disease and rheumatoid arthritis in mouse models." (PMID 34367180, 2021). "An elevated IL-6 level also occurs in various immune diseases, such as rheumatoid arthritis and Castleman disease, and nephropathies in multiple myeloma." (PMID 34425760, 2021). "A cytokine regularly highlighted for its importance in CSS is IL-6, a pleiotropic molecule whose signalling is targeted therapeutically in several inflammatory disease contexts, for instance, in rheumatoid arthritis and, notably, in the CSS condition HLH." (PMID 34564316, 2021). "However, this observational study is small (120 participants), had large numbers of patient stopping or switching therapy (60% switching biological therapy) and may be susceptible to confounding factors (patients receiving IL‐6 inhibition were older and had rheumatoid arthritis for longer)." (PMID 33393675, 2021). "IL-37 has an anti-inflammatory effect in rheumatoid arthritis, reduces the secretion of IL-1β, IL-6, and TNF-α and MIP-2, and mediates M2 macrophage polarization." (PMID 34842603, 2021). "Earlier studies have revealed that IL-22 is highly expressed in chronic inflammatory conditions including psoriasis, IBD, and rheumatoid arthritis and induces expression of proinflammatory molecules like IL-6, IL-1, GM-CSF, and LPS-binding protein." (PMID 33451114, 2021). "UC-MSCs have been used to modulate IL-6 in the body: for example, the levels of IL-6 decreased around 50% three months after treatment in a study of 172 patients with rheumatoid arthritis." (PMID 33853637, 2021). "Elevated levels of IL‐6 and IL‐27 have been observed in chronic inflammatory conditions, such as rheumatoid arthritis and a lot of hematopoietic malignancies and solid tumours." (PMID 33277798, 2021). "This multi-center, retrospective study aimed to clarify retention rates and reasons for discontinuation of either tumor necrosis factor inhibitors (TNFi) or interleukin-6 inhibitors (IL-6i) in patients with elderly-onset rheumatoid arthritis (EORA)." (PMID 33858490, 2021). "Simvastatin was shown to inhibit the release of IL-6 and IL-8 from colorectal cell lines and in patients with rheumatoid arthritis." (PMID 34063134, 2021).
rheumatoid arthritis (continued). "IL-6 has various functions in the pathogenesis of sJIA in children and rheumatoid arthritis in adults, in the sense that it induces an acute phase response as well as activates immune reactions and hematopoiesis." (PMID 32911717, 2020). "IL-6 concentrations have been found to correlate with levels of joint erosion in rheumatoid arthritis sufferers, indicating a role in bone resorption." (PMID 33584321, 2020). "Targeting the inhibition of IL-6 by bLF has positive clinical implications, for instance for patients with rheumatoid arthritis that fail anti-TNF therapy." (PMID 32477333, 2020). "The IL-6 expression by IL-1β stimulated fibroblast-like synoviocytes derived form patients with rheumatoid arthritis was successfully inhibited by piperine treatment." (PMID 33708109, 2020). "IL-6 is well-known for its effects in diabetes, atherosclerosis, prostate cancer, encephalitis and also rheumatoid arthritis, acting as a pro-inflammatory cytokine reinforcing the inflammatory states." (PMID 32235786, 2020). "The study of tocilizumab has led to new findings, such as IL-6 playing major roles in angiogenesis and cartilage-bone destruction, which are important for the progression of rheumatoid arthritis." (PMID 32743515, 2020). "Sarilumab is an additional IL-6 targeted monoclonal antibody that has been approved in the treatment of rheumatoid arthritis." (PMID 32707537, 2020). "In conditions such as rheumatoid arthritis, blockade of TNFα leads to a subsequent decrease in IL-1 and IL-6, adhesion molecules and angiogenic factors such as vascular endothelial growth factor (VEGF)." (PMID 32903555, 2020). "Blockade of IL-6 signaling is a promising strategy for the treatment of chronic inflammatory conditions such as rheumatoid arthritis." (PMID 32456348, 2020). "IL6 is also a well-established therapeutic target for inflammatory diseases such as rheumatoid arthritis." (PMID 31917819, 2020). "In the included studies, IL-6 signaling pathway inhibitors were administered for the following diseases: nine studies in rheumatoid arthritis patients, one in Castleman’s disease patients and one in obese patients." (PMID 32878032, 2020). "Pro-inflammatory cytokines including IL-6, IL-1β, and TNF-α are secreted from macrophages after LPS treatment, and they are linked to various chronic diseases, including rheumatoid arthritis, type II diabetes, and cancer." (PMID 32238770, 2020). "Several studies have shown increased levels of IL-6 and IL-8 in peripheral blood mononuclear cells or the bone marrow of patients with rheumatoid arthritis." (PMID 33072083, 2020). "Baricitinib and ruxolitinib, both targeting JAK1 and JAK2 which are the dominant kinases downstream of IL-6, have been approved for the treatment of myelofibrosis and rheumatoid arthritis, respectively." (PMID 33384605, 2020). "Functional studies have indicated that a cross-talk between the IL6 signaling and voltage-gated channels participates in the regulation of nociception in response to trauma or inflammatory disease such as rheumatoid arthritis." (PMID 31932740, 2020). "Such approved drugs include inhibitors of TNF-α (e.g., etanercept and adalimumab), IL-6 (e.g., tocilizumab), and IL-1β (e.g., canakinumab) signaling for immune diseases such as rheumatoid arthritis and Crohn’s disease." (PMID 33291425, 2020). "PGE2, IL-6, IFN-β, and IL-1β have been implicated in inflammatory and autoimmune diseases, including rheumatoid arthritis and systemic lupus erythematous." (PMID 32290603, 2020). "In mouse models of rheumatoid arthritis and lupus, PR-957 treatment reduces cellular infiltration, autoantibody levels, and cytokine production, including IL-2, IL-6, IL-23, IFN-γ, and TNF-α, effectively alleviating the inflammatory response." (PMID 32595507, 2020).
rheumatoid arthritis (continued). "On the other hand, in agreement with the current study, paeonol decreased the TLR4/NF-κB/TNF-α/IL-6 inflammatory signaling pathway in lipopolysaccharide-induced acute lung injury and IL-1β-induced human fibroblast-like synoviocyte rheumatoid arthritis." (PMID 32104151, 2020). "IL-6 antagonists have been proposed for the treatment of cachexia in patients with cancer or rheumatoid arthritis." (PMID 33260150, 2020). "In other chronic inflammatory diseases such as inflammatory bowel disease, peritonitis, rheumatoid arthritis, asthma as well as in colon cancer, IL-6 trans-signaling is critically involved in the maintenance of the disease state." (PMID 32209102, 2020). "Given IL-6’s implication in disease states, several agents inhibiting the IL-6 signaling pathway have been developed as pharmacological treatments for some of these diseases, e.g., rheumatoid arthritis, Castleman’s disease and prostate cancer." (PMID 32878032, 2020). "IL-6 is one of the main cytokines related to developing inflammatory and autoimmune diseases such as rheumatoid arthritis, systemic sclerosis, systemic lupus erythematosus, asthma and other diseases." (PMID 32942640, 2020). "It is essential to identify the rheumatoid arthritis patients who will respond to anti‐IL‐6 therapy." (PMID 32162496, 2020). "Gadient and Patterson reported that, in addition to the systemic acute phase reaction, IL-6 and LIF are associated with several acute and chronic inflammatory diseases, including rheumatoid arthritis and bacterial meningitis." (PMID 31940845, 2020). "Tofacitinib and baricitinib, two specific JAK inhibitors that have been used as therapeutics for rheumatoid arthritis, seemingly exert their pharmacological effects by blocking IL-6/JAK/STAT signaling." (PMID 32079226, 2020). "IL-6 concentrations were measured in the blood and urine of patients with rheumatoid arthritis, systemic lupus erythematosus and glomerulonephritis." (PMID 32743515, 2020). "IL-1, IL-6, and tumor necrosis factor α (TNFα) play a major pathological role in rheumatoid arthritis through NF-ĸB and JAK/STAT pathways." (PMID 32079226, 2020). "In collaboration with Dr. Shiro Shimizu of Kanazawa medical Univ., higher levels of IL-6 were found in the blood and synovial fluid of patients with rheumatoid arthritis." (PMID 32743515, 2020). "The anti-IL-6 mAb olokizumab is currently undergoing a phase III clinical trial for rheumatoid arthritis (ClinicalTrials.gov identifier NCT02760368)." (PMID 32765502, 2020). "Theacrine attenuated rheumatoid arthritis via the suppression of IL-6 and the activation of TGF-β by the TGF-β/SMAD pathway." (PMID 33392238, 2020). "Inhibitors of the IL-6 signaling pathway, such as tocilizumab, are frequently administered for the treatment of immune diseases, e.g., rheumatoid arthritis and multicentric Castleman’s disease." (PMID 32878032, 2020). "Inflammatory cytokines including IL‐6 are known to contribute to the pathogenesis of rheumatoid arthritis, and monoclonal antibody such as tocilizumab is effective to some patients but not all rheumatoid arthritis with high remission rate." (PMID 32162496, 2020). "Interleukin-6 (IL-6) is a pleiotropic cytokine that plays a key role in the pathogenesis of rheumatoid arthritis." (PMID 32264972, 2020). "In rheumatoid arthritis, IL-6 produced by synovial fibroblasts contributes to the autoimmunity associated with this disease." (PMID 33194837, 2020). "In patients with rheumatoid arthritis, miR-9-5p is downregulated by IL-6 and TNF-α and has a preventive effect on the development of peripheral neuropathy." (PMID 32751105, 2020). "These include tocilizumab, which is widely used in rheumatoid arthritis and blocks Interleukin-6 (IL-6), a combination of emapalumab, anakinra and sarilumab, and interferons." (PMID 33071775, 2020). "IL-6 plays a pro-inflammatory role in the stress response during acute illness and chronic inflammation, such as rheumatoid arthritis." (PMID 33101052, 2020).
rheumatoid arthritis (continued). "HAT inhibition resulted in the significantly reduced acetylation of histone H3 levels in the IL-6 promoter, as well as decreased IL-6 mRNA expression and IL-6 protein release by rheumatoid arthritis synovial fibroblasts." (PMID 32756302, 2020). "Tocilizumab and sarilumab are interleukin-6 (IL-6) inhibitors approved for the treatment of rheumatoid arthritis." (PMID 32372695, 2020). "Antibody therapies against both are currently being tested in clinical trials for cancer, and a blocking antibody against IL-6 is FDA approved to treat rheumatoid arthritis and acute cytokine release syndrome, a side effect of CAR-T cell therapy." (PMID 32493933, 2020). "AIF1 plays a critical role in the regulation of massive synovial proliferation and the production of IL6 in rheumatoid arthritis." (PMID 32110485, 2020). "These three cytokines were selected because they are widely involved in the pathophysiology of several arthritis including rheumatoid arthritis; pathology in which IL‐1, IL‐6 and TNF‐α are therapeutic targets." (PMID 33159500, 2020). "Red cell distribution width is positively correlated with tumor necrosis factor alpha (TNF‐alpha) and interleukin (IL)‐6 in rheumatoid arthritis, suggesting that RDW is a potential adjunct marker that reflects an inflammatory process." (PMID 32196750, 2020). "Accordingly, enhanced IL-6 signaling in serum and tissues has been found in rheumatoid arthritis, systemic lupus erythematosus, and RR-MS patients." (PMID 32655367, 2020). "For example, antibodies targeting IL‐6 are approved for the treatment of rheumatoid arthritis and a number of IL‐6 targeting monoclonal antibodies are under evaluation as treatments for severe COVID‐19 disease." (PMID 32438473, 2020). "In this study, we show that CBD increases intracellular calcium levels, reduces cell viability and IL-6/IL-8/MMP-3 production of rheumatoid arthritis synovial fibroblasts (RASF)." (PMID 32873774, 2020). "Drugs that suppress IL-6 release, such as tocilizumab, are used in the treatment of rheumatoid arthritis and juvenile rheumatoid arthritis, and are among the possible future treatment options of pustular psoriasis." (PMID 32811699, 2020). "We can refer only to previous reports, which showed that IL-17 (20 ng/ml) increases the secretion of IL-6 and IL-8, inducing rheumatoid arthritis (RA), and has immunomodulatory effects on multiple sclerosis (MS)." (PMID 33082827, 2020). "Exposure of human macrophages to IgG-ICs in conjunction with TLR ligands amplifies production of TNF-α, IL-1β, and IL-6, all of which play critical roles in the pathology of diseases such as rheumatoid arthritis (RA)." (PMID 32719679, 2020). "It has been reported that IL-6 levels are increased in various autoimmune diseases including rheumatoid arthritis (RA), multiple sclerosis (MS) and lupus, and targeting IL-6 can be an effective approach in the treatment of several autoimmune diseases." (PMID 32133007, 2020). "Rheumatoid arthritis is characterized by hyperproduction of IL-6, and IL-6 serum levels correlate well with combined indicators of disease activity and progression of bone tissue destruction." (PMID 33266394, 2020). "It has been shown that patients suffering from OA or rheumatoid arthritis had significantly higher concentrations of the pro-inflammatory cytokines IL6 and IL8 in their serum and synovial fluid than healthy subjects." (PMID 33339388, 2020). "The current study aimed to quantify Interleukin-6, -10, -17, and -23 levels in rheumatoid arthritis." (PMID 32300908, 2020). "For example, in the clinic, TNFα inhibitors are used with relatively high success in therapy of autoimmune diseases and inflammatory disorders, and therapies directed to IL-6 are used in rheumatoid arthritis." (PMID 33585241, 2020). "For instance, blockade of IL-6 or its α-receptor (IL-6R) by monoclonal antibodies has been successfully used to treat rheumatoid arthritis." (PMID 32456348, 2020).
rheumatoid arthritis (continued). "For example, the transfection of miR-451 mimics decreases the levels of TNF-α, IL-1β, and IL-6 in synovial fibroblasts isolated from rheumatoid arthritis patients." (PMID 31652441, 2019). "Dendritic cells that are present in the synovial fluid increase the release of TNF, IL-1β, IL-6, and IL-23 and stimulate Th17-cell differentiation, and thus IL-17 production in rheumatoid arthritis joints." (PMID 31295952, 2019). "Baricitinib is a JAK 1/2 inhibitor approved in the USA, EU, and Japan for rheumatoid arthritis, demonstrating potent inhibition of IL-6, D-dimer, CRP, TNF-α, IFN-α/β, and other pro-inflammatory cytokines." (PMID 31561750, 2019). "IL-6 trans-signaling is driven by ectodomain shedding of the IL-6R and has been shown to be a critical event in inflammatory diseases such as rheumatoid arthritis and inflammatory bowel disease." (PMID 31357561, 2019). "Beforehand, mouse models of rheumatoid arthritis had shown that IL-6 signaling drives disease progression by stimulating synovial hyperplasia, preservation of joint inflammation, and damage of underlying cartilage and bone." (PMID 31694340, 2019). "IL-6 inhibitors have been used in the treatment of rheumatoid arthritis, and DDZ’s metabolite equol has been reported to mitigate microglial activation and potentiate neuroprotection in central nervous system cells." (PMID 31878046, 2019). "IL-6 is widely present in various inflammatory responses, and therapeutic efficacy of blocking IL-6 has been proven in Castleman disease and inflammatory diseases (rheumatoid arthritis)." (PMID 31970102, 2019). "The KEGG pathway enrichment showed that IL-6 was enriched in rheumatoid arthritis, cytokine-cytokine receptor interaction, and TNF signaling pathway." (PMID 31139654, 2019). "Accordingly, circulating levels of both IL-6 and Hp strongly increased during chronic inflammatory conditions such as rheumatoid arthritis (RA) and DMD." (PMID 30862132, 2019). "IL-17A or IL-17 is involved in several chronic diseases, including rheumatoid arthritis (RA), and it upregulates other proinflammatory cytokines, including IL-1β and IL-6." (PMID 31614911, 2019). "IL-6 signaling initiates a range of degenerative and inflammatory processes during rheumatoid arthritis." (PMID 31694340, 2019). "IL-6 expression levels are elevated in some inflammatory reactions, such as infection, skin trauma, rheumatoid arthritis, and systemic lupus erythematosus." (PMID 30857352, 2019). "This is supported by previous reports that demonstrate that inhibition of HDAC activity in fibroblast-like cells and macrophages from patients with rheumatoid arthritis was able to block the production of IL-6 cytokines in those cells." (PMID 31626638, 2019). "Recently, biological products, such as anti-TNF-α neutralized antibody (etanercept, infliximab, and adalimumab, etc.,) and anti-IL-6 neutralized antibody (tocilizumab), which are drugs created by biotechnology, have been used for rheumatoid arthritis." (PMID 31847314, 2019). "SHW administration improved the various features of arthritis and rheumatoid arthritis including elevated serum levels of IL-6, TNF-alpha, type II collagen IgG, swelling of hind limbs, and infiltration of inflammatory cells in the synovial membrane." (PMID 30606189, 2019). "Elevated IL-6 levels are used to characterize autoimmune diseases, such as rheumatoid arthritis and inflammatory bowel disease." (PMID 31296870, 2019). "Overexpression of both IL-6 and IL-1β is considered to be an important role in the pathophysiology of rheumatoid arthritis." (PMID 30915347, 2019). "Pharmacological inhibitors of IL-6 signaling, which are already used in the clinic to treat chronic disorders like rheumatoid arthritis, have been shown to induce beneficial effects in a suite of experimental models of degenerative diseases." (PMID 30862132, 2019).